COX10 (cytochrome c oxidase assembly factor heme A:farnesyltransferase COX10)
Description:
Converts protoheme IX and farnesyl diphosphate to heme O.
Synonyms: MC4DN3
Tractability: Antibody: UniProt predicts a signal peptide or a membrane-spanning region. PROTAC: ubiquitination databases record sites on it.
Gene: Protein-coding gene on chromosome 17 (14,069,490 to 14,231,736, forward strand). Ensembl gene ENSG00000006695.
Subcellular location: Mitochondrion membrane
Subcellular location (Human Protein Atlas): Mitochondria; Cytosol; Nucleoli
Pathways (Reactome):
Metabolism: Heme biosynthesis
Gene Ontology:
Molecular function: geranylgeranyl diphosphate synthase activity; protoheme IX farnesyltransferase activity; prenyltransferase activity; transferase activity, transferring alkyl or aryl (other than methyl) groups
Biological process: heme A biosynthetic process; respiratory chain complex IV assembly; heme biosynthetic process; cytochrome complex assembly
Cellular component: cytochrome complex; mitochondrion; mitochondrial inner membrane; membrane; mitochondrial matrix; mitochondrial membrane
Genetic constraint (gnomAD): Loss-of-function variants: 28 observed, 41.09 expected, observed/expected ratio (o/e) 0.68, 90% interval 0.5 to 0.93. The upper end of that interval is the gene's LOEUF score, 0.93, which puts it in group 3 of 6, group 1 being the genes least tolerant of losing a copy. Missense variants: 475 observed, 565.92 expected, observed/expected ratio (o/e) 0.84, 90% interval 0.78 to 0.91. Synonymous variants: 222 observed, 226.03 expected, observed/expected ratio (o/e) 0.98, 90% interval 0.88 to 1.1.
Gene-disease validity (ClinGen):
ClinGen rates the evidence that COX10 causes each of these diseases.
mitochondrial disease (autosomal recessive): Definitive.
Leigh syndrome (autosomal recessive): Moderate. A progressive neurological disease defined by specific neuropathological features associating brainstem and basal ganglia lesions.
Homologues: Orthologues: macaque COX10 (95% identical), chimpanzee COX10 (86% identical), dog COX10 (86% identical), guinea pig COX10 (85% identical), rabbit COX10 (85% identical), pig COX10 (83% identical), mouse Cox10 (82% identical), rat Cox10 (81% identical), zebrafish cox10 (59% identical), tropical clawed frog cox10 (45% identical), Drosophila melanogaster Cox10 (41% identical), Caenorhabditis elegans cox-10 (37% identical). Paralogues in human: COQ2 (20% identical).
Diseases named in the same sentence as COX10 in open-access papers:
COX10 is named in the same sentence as 56 diseases in open-access papers, as found by Europe PMC text mining. Sharing a sentence is not in itself a finding about the gene and the disease. The quoted sentences say what the papers report.
Mitochondrial myopathy (8 papers, 2012 to 2025). "For instance, COX10 encodes a key component of cytochrome c oxidase, with mutations linked to congenital muscular dystrophy and mitochondrial myopathies." (PMID 39595553, 2024). "Interestingly, these biomarkers were first identified in mouse models of mitochondrial myopathy, including those with a Cox10 deficiency." (PMID 36301669, 2023). "Moreover, a Krebs cycle anaplerosis with α-ketoglutarate in cybrids with a mutation in the MT-ATP6 gene and in a murine model of COX10−/− mitochondrial myopathy has demonstrated the ability to attenuate the alterations derived from mitochondrial failure." (PMID 37446148, 2023). "Increased susceptibility of female mice to mitochondrial myopathy was also observed in a muscle-specific knockout mouse model of COX10 and may account to the effect of testosterone in muscle mass." (PMID 25802402, 2015). "Furthermore, skm-specific transgenic expression of PGC-1α prevents the decline in COX activity during aging in mice and the reduction in COX activity in a mouse model of mitochondrial myopathy caused by a skm-specific deletion of COX10." (PMID 22272266, 2012). "To investigate if GCs signaling pathway participates in muscle and fat wasting and contributes to mitochondrial myopathy, we treated COX10 KO mice with the GC receptor (GR) antagonist RU‐486." (PMID 37222423, 2023). "In our study, we compared m.8344A>G MERRF human patients affected by severe mitochondrial myopathy to a mouse model of mitochondrial myopathy, the muscle‐specific COX10 KO mouse." (PMID 37222423, 2023). "In COX10 KO and WT brains, differential aspartate to glutamate and glutamine to glutamate ratios point to an interesting linkage between muscle health and brain neurotransmitter signaling: mitochondrial myopathy alters glutamine, glutamate and aspartate signaling near the NAc." (PMID 40100251, 2025).
Leigh syndrome (6 papers, 2021 to 2024). "COX10 mutations in humans trigger mitochondrial causes such as Leigh syndrome, a factor that may increase the risk of Alzheimer’s disease." (PMID 36768207, 2023). "Similar to the spectrum of different clinical phenotypes associated with mutations in COX10, COX-deficient patients bearing mutations in COX15 also present with a wide variety of symptoms, resulting in cardiomyopathy or Leigh syndrome." (PMID 38612624, 2024). "Two exons are also deleted at the heterozygous state in the COX10 gene responsible for the Leigh syndrome." (PMID 33420067, 2021).
cardiomyopathy (3 papers, 2023 to 2025). A disease of the heart muscle or myocardium proper. "A recent study also highlighted ATF4’s protective role in preventing ferroptosis in cardiomyopathy caused by a Cox10 deficiency." (PMID 40227255, 2025). "Cox10−/− mice develop early-onset lethal cardiomyopathy, which is associated with OXPHOS deficiency, lysosomal defects, and an aberrant mitochondrial morphology." (PMID 37793777, 2023). "Impairing GPX4 upregulation induced by OXPHOS deficiency through the inhibition of the integrated stress response, by knocking out either the mitochondrial protease OMA1 or its substrate DELE1, aggravates the cardiomyopathy of Cox10-/- mice by decreasing GPX4 to WT levels, thus inducing ferroptosis." (PMID 37505079, 2023).
meningioma (3 papers, 2016 to 2025). A generally slow growing tumor attached to the dura mater. "Elevated levels of COX10 are negatively correlated with the prognosis of patients with gliomas and meningiomas and may lead to aberrant phosphorylation." (PMID 40620061, 2025).
Encephalopathy (2 papers, 2020 to 2023). Encephalopathy is a term that means brain disease, damage, or malfunction. "Accordingly, Cox10 interference was considered as a model for encephalopathy and was not applicable as a model for age-related dementia." (PMID 32265651, 2020).
lung carcinoma (2 papers, 2024 to 2025). "In lung cancer and melanoma, while a deficiency in COX10 decreased tumor neovascularization and decelerated tumor growth, it also led to an expanded region of ischemic necrosis and facilitated tumor metastasis." (PMID 40620061, 2025). "In lung cancer and melanoma, although COX10 deficiency reduces tumour neovascularization and slows tumour growth, it likewise leads to an increase in the area of avascular necrosis and promote tumour metastasis." (PMID 38843392, 2024).
Stroke (2 papers, 2020 to 2023). Sudden impairment of blood flow to a part of the brain due to occlusion or rupture of an artery to the brain. "Based on the role of metabolism in stroke, we extracted seven genes related to the “porphyrin metabolism” and “glycine, serine and threonine metabolism” pathways, including ALAS2, FECH, COX10, GCAT, HMBS, PGAM2, and AOC2." (PMID 36968495, 2023).
asthma (1 paper, 2022). "Based on the available diagnosis information, we assigned the 42 asthma cases into comorbidity subgroups; only subgroups 5 and 3 involving three genes (OSTF1, COX10, and FAM129B) contained five or more individuals, and were included in these analyses." (PMID 36344522, 2022). "OSTF1 expression was significantly reduced while COX10 was overexpressed in asthmatics in subgroup 5 “Musculoskeletal”, compared to the expression levels in the non-asthma controls or in the asthma cases not in subgroup 5." (PMID 36344522, 2022).
cardiac hypertrophy (1 paper, 2024). "Because cardiac hypertrophy is caused by an increase in myocyte size, which depends on mitochondrial proliferation, the reduced mitochondrial mass in Cox10−/−Opa1v1Δ4 hearts may limit hypertrophic cell growth." (PMID 39093974, 2024). "Hypertrophic signature genes were up-regulated relative to WT in the hearts of both Cox10−/− and Cox10−/−Opa1v1Δ4 mice, although we did not observe cardiac hypertrophy in the latter mouse line." (PMID 39093974, 2024).
Charcot-Marie-Tooth (CMT) disease (1 paper, 2019). "Mutations in COX6A1 and COX10 are associated with Charcot-Marie-Tooth (CMT) disease and mitochondrial disorders." (PMID 31834878, 2019).
colorectal cancer (1 paper, 2019). A primary or metastatic malignant neoplasm that affects the colon or rectum. "COX10 (Cytochrome C Oxidase Assembly Homolog 10) is a member of a 14-gene classifier for colorectal cancer metastasis, identified by differential gene expression analysis of early and late stage primary colorectal cancer." (PMID 31019223, 2019).
diabetes (1 paper, 2017). "We previously showed that decrease in nucleus encoded COX4I1 and COX10 depended on obesity and insulin resistance and diabetes." (PMID 28122051, 2017).
dilated cardiomyopathy (1 paper, 2024). Cardiomyopathy which is characterized by dilation and contractile dysfunction of the left and right ventricles. "Accordingly, loss of Cox10 in the heart leads to OXPHOS deficiency and early-onset dilated cardiomyopathy." (PMID 39093974, 2024).
glaucoma (1 paper, 2022). Increased pressure in the eyeball due to obstruction of the outflow of aqueous humor. "Metabolic dysfunction has been reported in RGCs from glaucoma patients and in animal models, and we have reported the sensitivity of MG to OHT-associated hypoxia, so we examined the impact of MG-specific COX10 knockout on RGC survival following 4 weeks of ocular hypertension." (PMID 36497016, 2022).
leukodystrophy (1 paper, 2021). Leukodystrophies are a group of rare, progressive, metabolic, genetic diseases that affect the brain, spinal cord and often the peripheral nerves. "Isolated leukodystrophy is unusual in patients with LS and SURF1 mutations, therefore other mitochondrial diseases, such as COX10 gene mutations and metabolic disorders, should be considered for diagnosis." (PMID 34943053, 2021).
MERRF (1 paper, 2023). A mitochondrial encephalomyopathy characterized clinically by a mixed seizure disorder, myoclonus, progressive ataxia, spasticity, and a mild myopathy. "Alanine, a glucogenic amino acid, was elevated in plasma from COX10 KO mice and MERRF patients." (PMID 37222423, 2023). "Furthermore, these responses in the COX10 KO mouse model recapitulate findings from studies of symptomatic MERRF patient muscle and plasma." (PMID 37222423, 2023).
mitochondrial complex IV deficiency (1 paper, 2022). "The first cohort was assembled focusing on the COX10 gene, defects of which cause mitochondrial complex IV deficiency (OMIM# 220110) inherited as an AR trait." (PMID 36180924, 2022).
myocardial ischemia (1 paper, 2024). A disorder of cardiac function caused by insufficient blood flow to the muscle tissue of the heart. "These thorough results demonstrated that MTH increases the expression of COX10 that has been modified by O-GlcNAcylation, reducing mitochondrial damage and dysfunction caused by myocardial ischemia–reperfusion injury." (PMID 38778315, 2024). "This study investigated the relationship between shallow hypothermia treatment improving myocardial ischemia–reperfusion injury and the O-GlcNAcylation level of COX10." (PMID 38778315, 2024). "Our research results indicate that MTH upregulates the O-GlcNACylation level of COX10, improves mitochondrial function, and inhibits the expression of ROS to improve myocardial ischemia–reperfusion injury." (PMID 38778315, 2024). "At the same time, we explored the impact of COX10 on O-GlcNAcylation levels through research methods such as immunofluorescence, IP, and WB to clarify the important role of mitochondrial damage in myocardial ischemia–reperfusion." (PMID 38778315, 2024). "In summary, MTH activates OGT mediated O-glycosylation modified COX10 to regulate mitochondrial function and improve myocardial ischemia–reperfusion injury, which provides important theoretical basis for the clinical application of MTH." (PMID 38778315, 2024). "Through further mechanism research, we have identified that MTH can alleviate mitochondrial damage induced by myocardial ischemia–reperfusion injury by upregulating the O-GlcNAcylation level of cytochrome C oxidase COX10 and promoting COX10 transfer into mitochondria." (PMID 38778315, 2024). "Therefore, we propose a hypothesis that mild hypothermia therapy may improve mitochondrial function by modulating the O-GlcNAcylation status of COX10 O-GlcNAcylation, ultimately alleviating myocardial ischemia–reperfusion injury." (PMID 38778315, 2024).
Obesity (1 paper, 2017). Accumulation of substantial excess body fat. "We found that low COX4I1 and low COX10 in monocytes and adipose tissues of patients and in adipose tissues of double-knock-out mice were associated with obesity and type 2 diabetes." (PMID 28122051, 2017).
oral cancer (1 paper, 2022). "To confirm that ZEB1 could physically bind to the SIRT3 and COX10 promoter regions in oral cancer cells, we conducted ChIP and Dual-luciferase reporter assays." (PMID 35963855, 2022).
prostate carcinoma (1 paper, 2026). A carcinoma that arises from epithelial cells of the prostate gland. "SETD6 KO GO Group 1 is related to cell proliferation and includes DHX37 and COX10, which both are associated with prostate cancer." (PMID 41540805, 2026).
type-2 diabetes (1 paper, 2019). "COX proportional hazards regression analysis confirmed that MT-COI and STRN, but not COX10, were independently related to time to new event adjusting for age, gender, (ex)-smoking, BMI, blood pressure, type-2 diabetes, HDL- and LDL-cholesterol, triglycerides and hs-C-reactive protein." (PMID 31821324, 2019).
myopathy (6 papers, 2012 to 2023). A disease of the muscle in which the muscle fibers do not function properly. "First, we assessed protein markers in COX10 KO muscle during disease progression at 50 days (early stage of myopathy), 100 days (the age of weight loss onset, intermediate stage of myopathy) and ≥ 170 days (late stage of myopathy)." (PMID 37222423, 2023). "Cox10 is an assembly factor of complex IV, and Cox10 deletion in skeletal muscle is associated with diminished cIV activity accompanied by myopathy." (PMID 36154948, 2022). "When the levels of these enzymes were analyzed longitudinally within the COX10 KO group, a progressive increase in levels was paralleled by an apparent worsening of the myopathy." (PMID 37222423, 2023). "COX10 knockout mice began to develop progressive myopathy at three months of age, and the myopathy was worsened by aging, particularly in female mice." (PMID 35204431, 2022). "In COX10 KO muscle, upregulated amino acid oxidation through the TCA cycle commences at an early stage of myopathy and increases with age." (PMID 37222423, 2023). "We found increased transcript levels of Fgf21 in COX10 KO muscle and chronically elevated levels of circulating FGF21 protein commencing from the earliest stage of myopathy (9‐, 4‐, and 5‐fold at 50, 100, and 200 days, respectively)." (PMID 37222423, 2023).
tumor (6 papers, 2012 to 2025). "In addition, COX10-deficient cells upregulate glycolysis, which is the backbone of tumour cell metabolism." (PMID 38843392, 2024). "Thus, COX10 deficiency does more harm than good during tumour progression." (PMID 38843392, 2024). "In both models, tumour growth was significantly reduced in the cox10ECKO mice compared with cox10-competent hosts (cox10fl/fl)." (PMID 32694534, 2020). "Even for the therapy-naïve study cohort, differential gene expression was a significant prognosticator within tumor sets defined by their WHO grades (WHO°I: AURKB, COX10, ECT2, UBE2C; WHO°II: LEPR, MN1; WHO°III: PTTG1, UBE2C)." (PMID 26894859, 2016).
cancer (5 papers, 2016 to 2025). A tumor composed of atypical neoplastic, often pleomorphic cells that invade other tissues. "Interestingly, many mitochondria-associated ELIdn genes were downregulated in fibroblasts with metastatic transition of cancer, including COX10, MSTO1, CPT2, and MDH1B." (PMID 35565326, 2022). "However, reports regarding the function of COX10 in cancer are limited." (PMID 40620061, 2025). "Interestingly, the expression patterns of DCAF4, COX10, and TGOLN2 presented the best tool set to identify and separate cell lines with their respective irinotecan-resistant variants from other pairs of parental–resistant CRC cells lines that were delivered from different cancer locations or stages." (PMID 35885025, 2022). "The PPI network analysis further revealed key interactors such as COX10 and FECH, which are involved in mitochondrial function and heme metabolism, supporting the idea that HCCS could influence mitochondrial dynamics and cellular energy production in cancer cells." (PMID 41476662, 2025).
mitochondrial disease (4 papers, 2020 to 2023). "Iron supplementation significantly elevated the expression of Cox10, the mutations of which are associated with mitochondrial disease, and Bola3 and Isca2, the mutations of which are associated with MMDS and/or oxidative phosphorylation activity." (PMID 34031430, 2021).
neurodegenerative disease (2 papers, 2017 to 2026). A disorder of the central nervous system characterized by gradual and progressive loss of neural tissue and neurologic function. "Relevant to the hallmarks of neurodegenerative disease, Cd38‐deficient astrocytes also had disruptions to genes that regulate DNA/RNA functions (Trex1), protein homeostasis (Ubb), and cellular bioenergetics (Cox10)." (PMID 41400119, 2026). "In COX10 knockout mice, bezafibrate increases mitochondrial ATP synthesis and decreases astrocyte proliferation and inflammatory factors,suggesting that bezafibrate has a potential significance in the treatment of neurodegenerative diseases." (PMID 29359159, 2017).
COX10 also shares sentences with these, for which no sentence is quoted: cardiac failure (2 papers); glioma (2); hypertrophic cardiomyopathy (2); infection (2); melanoma (2); osteosarcoma (2); Alzheimer disease (1); arteriovenous malformations (1); atherosclerosis (1); cognitive decline (1); colon cancer (1); congenital muscular dystrophy (1); coronary artery disease (1); encephalomyopathies (1); hereditary neuropathy with liability to pressure palsies (1); Insulin resistance (1); ischemia (1); lactic acidosis (1); lymphoma (1); metabolic disorders (1); mitochondrial encephalomyopathies (1); Mitochondrial encephalopathy (1); myocardial infarction (1); neuropathy (1); ocular hypertension (1); OXPHOS disease (1); peripheral neuropathy (1); pulmonary hypertension (1); status epilepticus (1).